FBP2 (fructose-bisphosphatase 2)
Diseases named in the same sentence as FBP2 in open-access papers:
FBP2 is named in the same sentence as 40 diseases in open-access papers, as found by Europe PMC text mining. Sharing a sentence is not in itself a finding about the gene and the disease. The quoted sentences say what the papers report.
sarcoma (9 papers, 2020 to 2024). A usually aggressive malignant neoplasm of the soft tissue or bone. "A recent study utilized several metabolomic techniques such as unbiased mass spectrometry and isotope tracing to demonstrate that the loss of fructose-1,6 bisphosphatase 2 (FBP2) is a key event during sarcoma progression and a potential therapeutic target [41••]." (PMID 35171456, 2022). "It has been demonstrated that FBP2 impedes the progression of sarcoma by hindering mitochondrial biogenesis." (PMID 39763587, 2024). "Complementary research in sarcoma has ascertained that FBP2 is epigenetically silenced across various sarcoma subtypes and its presence inhibits cellular proliferation." (PMID 38034101, 2023). "FBP2 inhibits sarcoma growth by antagonistic action of cytosolic FBP2 to glycolysis, and by restraining action of the nuclear FBP2 to mitochondrial energetic respiration." (PMID 36077431, 2022). "Additionally, FBP2 has been demonstrated to impede the progression of sarcomas by inhibiting mitochondrial biogenesis." (PMID 39763587, 2024). "In addition to small molecule compounds that modulate the expression of TFAM, the oncogene c-Myc promotes nuclear transcription of TFAM, facilitating sarcoma growth, while Fructose-1,6-Bisphosphatase 2 (FBP2) overexpression inhibits c-Myc-mediated transcriptional regulation of TFAM." (PMID 38589371, 2024). "Upregulation of FBP2 could inhibit sarcoma cell and tumor growth in vitro and in vivo." (PMID 35571245, 2022). "Hspb7, Mb, Cox7a1, Fbp2, and Scara5 have all previously been identified as tumor suppressor genes in breast cancer, non-small cell lung cancer, gastric cancer, sarcoma, and hepatocellular carcinoma, wherein they can suppress tumor cell invasion, proliferation, and migration." (PMID 34194323, 2021). "Indeed, FBP2 is strongly downregulated in different types of sarcoma, while FBP2 re-expression in sarcoma cells severely inhibits tumor cell growth both in vitro and in vivo, showing a possible tumor-suppressive role of FBP2." (PMID 32102348, 2020). "Specifically, c‐Myc colocalizes with nuclear FBP2 at the TFAM binding site, leading to the inhibition of TFAM expression and, consequently, sarcoma tumorigenesis." (PMID 38034101, 2023). "As was reported, FBP2 is absent in numerous STS subtypes, and reintroduction of FBP2 has been observed to significantly slow the growth of sarcomas." (PMID 39763587, 2024).
gastric cancer (8 papers, 2013 to 2024). A primary or metastatic malignant neoplasm involving the stomach. "The lowered FBP2 expression in gastric cancer is associated with poor survival and tumorigenesis, as lowly expressed in gastric cancer, triggering glycolysis and proliferation." (PMID 36077431, 2022). "The promoter region of fructose-bisphosphatase 2 (FBP2) in gastric cancer is densely methylated to promote glucose metabolism." (PMID 35004688, 2021). "In gastric cancer cells, studies have found that FBP2 overexpression significantly reduces the levels of ATP and lactate through interference of the Akt-mTOR pathway." (PMID 29556139, 2018). "Expression of FBP1 and FBP2 was significantly downregulated in gastric cancer cell lines and gastric carcinomas (GCs) due to promoter hypermethylation." (PMID 29556139, 2018). "Here, we investigated the potential role of fructose-1,6-bisphosphatase-2 (FBP2), the enzyme that catalyses the hydrolysis of fructose-1,6-bisphosphate to fructose-6-phosphate and inorganic phosphate in glucose metabolism, in gastric cancer (GC) development." (PMID 24063558, 2013). "FBP1 and FBP2 are less expressed in gastric cancer due to the promoter methylation." (PMID 36077431, 2022). "FBP2 expression increased both subpopulations in gastric cancer cells." (PMID 29556139, 2018). "This action should be particularly interesting for treatment of cancers with poor prognosis (such as gastric cancer, brain metastatic breast cancers) expressing low FBP2, because as explained by Liu and Zhang, FBP2 is 1000 times more sensitive to inhibition by Ca2+." (PMID 30455595, 2018). "Bisulphite genomic sequencing (BGS) in gastric cancer cell lines revealed that the FBP2 promoter region was densely methylated, and treatment of GC cells with the demethylation reagent, 5-aza-2-deoxycytidine (5-Aza), led to an increase in FBP2 expression." (PMID 24063558, 2013).
breast carcinoma (4 papers, 2018 to 2024). "The gene-gene interactions of deregulated glucose related genes in breast cancer, and it was found that deregulated glucose related genes show high interactions with PFKFB2, PFKFB4, FBP2, PCK2, ADH5 and other genes involved in glucose metabolism." (PMID 38173442, 2024). "In brain metastatic breast cancer cells, knocking down FBP2 resulted in a significant amount of apoptotic cell death (as indicated by the increase incleaved PARP), whereas exogenous FBP2 significantly rescued cell death." (PMID 29556139, 2018).
soft tissue sarcoma (4 papers, 2022 to 2025). A malignant neoplasm arising from muscle tissue, adipose tissue, blood vessels, fibrous tissue, or other supportive tissues excluding the bones. "In soft tissue sarcomas, the gluconeogenic enzyme fructose-1,6-bisphosphatase 2 (FBP2) impedes tumor growth through two distinct mechanisms." (PMID 40658684, 2025). "Evidences have shown that fructose-1,6-bisphosphatase-2 (FBP2), a key enzyme for gluconeogenesis, was decreased in various human cells, such as cervical cancer and soft tissue sarcomas." (PMID 35571245, 2022). "Studies have indicated that the absence of FBP2 in soft tissue sarcoma cells can increase glucose absorption and utilization, suggesting FBP2’s role in inhibiting glycolysis." (PMID 40563444, 2025).
cervical cancer (3 papers, 2013 to 2022). A primary or metastatic malignant neoplasm involving the cervix. "Lowly expressed FBP2 negatively regulates aerobic glycolysis and inhibits proliferation of cervical cancer." (PMID 36077431, 2022). "FBP2 expression induces regression of aerobic glycolysis, growth and apoptotic death, leading to an anti-tumorigenic potential in cervical cancer." (PMID 36077431, 2022). "Our findings indicated that the FBP2 promoter was highly methylated in GC, which has been confirmed in other types of cancer such as brain, liver, breast, and cervical cancers." (PMID 24063558, 2013). "In cervical cancer, FBP2 expression is inhibited and indicates poor prognosis." (PMID 36077431, 2022). "FBP2 induces PKM2 ubiquitination, inhibiting proliferation and aerobic glycolysis in cervical cancers." (PMID 36077431, 2022).
lung carcinoma (3 papers, 2018 to 2021). "In lung cancer, FBP2 accumulated in cell nuclei during the S and G2 phases and interacted with histone family members and with several proteins involved in cell-cycle regulation and RNA processing." (PMID 29556139, 2018). "We show that, in contrast to current beliefs, in lung cancer cells, the predominant and strong interaction with the Hif1α form of Fbp is not the liver (Fbp1) but in the muscle (Fbp2) isoform." (PMID 31947613, 2020). "Moreover, our study demonstrates that in lung cancer cells, the predominant form of Fbp is Fbp2, not Fbp1, and that Hif1α interacts with Fbp2 much more strongly than with Fbp1." (PMID 31947613, 2020).
colorectal cancer (2 papers, 2017 to 2025). A primary or metastatic malignant neoplasm that affects the colon or rectum. "Besides, FBP2 was enriched in other pathways, including adherens junction, colorectal cancer, and the proteasome." (PMID 40093327, 2025).
hepatocellular carcinoma (2 papers, 2014 to 2021). A malignant tumor that arises from hepatocytes. "FBP-2 primarily supports migration in different hepatocellular carcinoma cells." (PMID 24392146, 2014).
oral squamous cell carcinoma (2 papers, 2022 to 2025). "The level of TRIM32 is increased in oral squamous cell carcinoma, and promotes disease progression by enhancing the ubiquitination and degradation of FBP2." (PMID 40507857, 2025). "However, the role of FBP2 in oral squamous cell carcinoma (OSCC) remains largely unclear." (PMID 35571245, 2022).
acute disseminated encephalomyelitis (1 paper, 2021). Acute disseminated encephalomyelitis (ADEM) is a demyelinating disorder of the central nervous system. "Furthermore, FBP2-related leukodystrophy is, no doubt, an extremely rare disorder and misinterpretation as an autoinflammatory disorder such as acute disseminated encephalomyelitis, the initial diagnosis in patients III.2 and III.5, may hamper recognition of further cases." (PMID 33977262, 2021).
cardiac hypertrophy (1 paper, 2020). "As a main result we found that AGAT−/− mice exhibited altered gene expression related to energy metabolism (Fbp2, Ucp2), cardiac hypertrophy and fibrosis (Nppa, Ctgf), immune response (Fgl2), and the conduction system of the heart (Dsc2, Ehd4, Hcn2, Hcn4, Scn4a, Scn4b)." (PMID 32179820, 2020).
cervical squamous cell carcinoma (1 paper, 2020). A squamous cell carcinoma arising from the cervical epithelium. "FBP2 is the least prognostic gene in only one cancer type, cervical squamous cell carcinoma and endocervical adenocarcinoma; CESC." (PMID 32807122, 2020).
developmental delay (1 paper, 2021). "The FBP2 variant was confirmed in the family members who had undergone exome sequencing and was also confirmed in patient IV.2 who has subsequently been shown to have leukoencephalopathy, developmental delay and behavioural problems." (PMID 33977262, 2021).
Facioscapulohumeral dystrophy (1 paper, 2024). Facioscapulohumeral muscular dystrophy (FSHD) is characterized by progressive muscle weakness with focal involvement of the facial, shoulder and limb muscles. "However, the muscle proteome analysis of Facioscapulohumeral dystrophy patients reveals decreased FBP2, whereas the upregulation of FBP2 was found in our study, indicating the distinct molecular mechanisms underlying muscle atrophy in various muscle atrophy models." (PMID 39858409, 2024).
leukodystrophy (1 paper, 2021). Leukodystrophies are a group of rare, progressive, metabolic, genetic diseases that affect the brain, spinal cord and often the peripheral nerves. "In conclusion, we report on a novel disorder that we termed FBP2-related leukodystrophy." (PMID 33977262, 2021). "This suggests a dominant negative effect of V115M-FBP2 on nuclear localization, presumably due to heteromerization of WT and mutant proteins and indicates that the nuclear functions of FBP2 are diminished in FBP2 related-leukodystrophy." (PMID 33977262, 2021). "FBP2-related leukodystrophy is a novel member of the group of remitting leukodystrophies." (PMID 33977262, 2021).
Leukoencephalopathy (1 paper, 2021). This term describes abnormality of the white matter of the cerebrum resulting from damage to the myelin sheaths of nerve cells. "In all available family members, the variant segregated with leukoencephalopathy on Sanger sequencing of the FBP2 gene." (PMID 33977262, 2021).
neuroblastoma (1 paper, 2023). Neuroblastoma (NB) is the most common solid, extracranial childhood tumor. "A recent study demonstrated that a signature consisting of five genes (AKR1C2, NCAN, AHCY, FBP2 and GALNT3) has potential prognostic values in neuroblastoma." (PMID 36701414, 2023).
nodular goiter (1 paper, 2021). Goiter characterized by discrete tissue mass(es) that may or may not produce thyroid hormones. "CHST6, FBP2, PPFIA4, and TGFBI proteins were all upregulated in THCA tissues compared with nodular goiter tissues." (PMID 33981593, 2021).
Sepsis (1 paper, 2024). Sepsis is defined as life-threatening organ dysfunction caused by a dysregulated host response to infection. "However, the current mechanism, the means by which FBP2 causes SIM in sepsis is unclear and requires further research." (PMID 39438952, 2024).
tumor (20 papers, 2013 to 2025). "First, by attenuating the Warburg effect, FBP2 reduces the dependence of tumor cells on glucose metabolism." (PMID 40658684, 2025). "Fructose-1,6-bisphosphatase 2 (FBP2), known as a rate-limiting enzyme in gluconeogenesis, is a tumor suppressor downregulated in various cancers." (PMID 35571245, 2022). "Kaplan-Meier survival analysis showed that 78.8% (41/52) of patients whose tumours exhibited low FBP2 expression had a poorer outcome than those with high FBP2 expression (P = 0.006)." (PMID 24063558, 2013). "The clonal origin of BGC823 cells with pcDNA3.1-FBP2 plasmid in the tumours was confirmed by staining the cells with an anti-FBP2 antibody." (PMID 24063558, 2013). "Multivariate analysis revealed that FBP2 expression was an independent prognostic predictor of GC (P = 0.019) in conjunction with tumour depth (P = 0.012)." (PMID 24063558, 2013). "FBP2 underexpression may contribute to GC tumor development by stimulating glucose metabolism and inhibiting cell proliferation." (PMID 35938042, 2022). "Taken together, this inverse correlation between FBP2 expression and cell proliferation suggested that FBP2 might act as a tumour suppressor gene in GC." (PMID 24063558, 2013). "Importantly, forced expression of FBP2 abrogated tumour formation of these GC cells in nude mice." (PMID 24063558, 2013). "The expression of differential genes related to PPP, including TKT, TKTL1, PGM1, GPI, FBP2, ALDOA and ALDOC, were all upregulated in WDLPS tumor samples, which were validated by Real-time Quantitative PCR (RT-qPCR)." (PMID 36557266, 2022). "In summary, the following marker genes were used for subsequent analysis in supratentorial tumours: RELA, ELL3, FBP2, PCP4L1, and MYO3A for detection of RELA+ tumours; and MRAP, IGF1, CAPS, and WWC1 for detection of YAP1+ tumours." (PMID 34314101, 2021). "The results prove that the expression levels of B3GALT6, DCN, FBP2 and GYS2 are lower in tumor samples and higher in normal tissue samples." (PMID 32489319, 2020). "The expression levels of B3GALT6, DCN, FBP2 and GYS2 are lower in tumor samples and higher in normal tissue samples." (PMID 32489319, 2020). "ENO3, FBP1, FBP2, GPD1, and ALDOB were all glycolytic pathway-related proteins with inhibitory effects on tumor." (PMID 33200655, 2020). "In addition, downregulation of FBP2 notably reduced FBP2 protein expression and upregulated Ki67, GLUT1, HK2, PKM2, and LDHA protein expressions in tumor tissues." (PMID 35571245, 2022). "Also, FBP2 (KHSRP in MetaCore), a member of the single-stranded DNA-binding protein family, is a furoxan-affected RBP that was found overexpressed in different cancers and that, depending on the tumor cell type, is involved in cell proliferation, migration, and drug resistance." (PMID 37570694, 2023). "Interestingly, there were a few studies concerning AHCY37 /NCAN38 /FBP2 /GALNT339 /AKR1C2 40 and T regulatory cells/macrophages, but most of these studies contradicted with our results in immunological manners, possibly because these studies were performed in different types of tumor." (PMID 35517412, 2022).
cancer (19 papers, 2013 to 2024). A tumor composed of atypical neoplastic, often pleomorphic cells that invade other tissues. "The two roles of FBP2 result in a reduction in the energy supply to the cancer cells, which provides an explanation for the frequent loss of FBP2 in STS and its potential as a therapeutic target." (PMID 39763587, 2024). "Elucidating the function of Cep89 and other validated candidates with putative roles in metabolism, e.g. CG3011, CG6084 and Fbp2, whose human ortholog has been linked to growth defects and cancer [e." (PMID 26751788, 2016). "As FBP2 acts in cervical tumor progression driven by the issued aerobic glycolysis, potentiating cancer aggression and resistance to anti-tumor therapy need to be uncovered." (PMID 36077431, 2022). "Remarkably, in hypoxic conditions, which are typical for many cancers, FBP2 ceases to interact with mitochondria and loses its pro-survival potential." (PMID 29383170, 2017). "FBP1 is recognised as the key enzyme of gluconeogenesis, and upregulated FBP1 has been shown to suppress cancer cell growth; recent studies indicate that FBP2 participates in glycogen synthesis from carbohydrate precursors." (PMID 24063558, 2013). "FBP2 overexpression suppresses glucose metabolism and inhibits cell proliferation in GC, while reduced FBP2 expression contributes to cancer development." (PMID 24063558, 2013). "Since methylation, one of the major epigenetic modifications of DNA capable of silencing gene transcription, plays an important role in cancer development, and contributes to the Warburg Effect, we also determined the methylation status of FBP2 promoter." (PMID 24063558, 2013). "However, fbp2, a gluconeogenic enzyme, exhibited the inhibition of gluconeogenesis in cancer cells which, in our findings, shows that this gene is downregulated." (PMID 35955446, 2022). "Furthermore, in cardiomyocytes and cancer cells, FBP2 has a recognized role in the regulation of the cell cycle." (PMID 33977262, 2021). "Furthermore, they suggest that the hypoxia/Hif1α-dependent regulation of the metabolism in cancer is modulated through a Fbp2-dependent sensing of the energy and redox state of a cell." (PMID 31947613, 2020). "Thus, re-expression of FBP2 might antagonize glycolysis and then decrease glucose uptake by cancer cells." (PMID 35571245, 2022). "Therefore, we hypothesize that the hypoxia/Hif1α-dependent regulation of the metabolism in cancer is modulated through Fbp2, and is based on the energy and redox state of a cell." (PMID 31947613, 2020). "However, in cancer cells, FBP2 acts as an anti-oncogenic/anti-proliferative protein." (PMID 29383170, 2017). "Taken together, restoration of FBP2 might be a novel and promising target for cancer therapy." (PMID 24063558, 2013). "Of the 10 proteins, the preceding text showed that some studies identified RRM2, PLOD2, MKI67, MCM5, and CKD1 promoted cancer progression and FBP1, FBP2, ENO3, GPD1, and ASS1 inhibited cancer progression, which was consistent with our results." (PMID 33200655, 2020). "One of the Fbp2 non-enzymatic functions is the reduction of hypoxia-inducible factor 1α (Hif1α) protein level in cancer cells." (PMID 39251668, 2024). "Since Fbp2 oligomerization state and thus, its role is regulated by AMP and NAD+—crucial indicators of cellular metabolic conditions—we hypothesize that the Hif1α-dependent regulation of the metabolism in cancer is modulated through Fbp2, a sensor of the energy and redox state of a cell." (PMID 31947613, 2020).
infection (2 papers, 2022 to 2023). The state of being infected such as from the introduction of a foreign agent such as serum, vaccine, antigenic substance or organism. "They further showed that FBP2 is relocalized from the nucleus to the cytoplasm during EV-A71 infection." (PMID 38257775, 2023). "Hence, EV-A71 infection cleaves FBP2 at the C-terminus to reverse its function from a negative to a positive regulator of viral translation while retaining the ability of FBP2 to bind to the 5′-UTR." (PMID 38257775, 2023).
metabolic disorders (1 paper, 2015). "In our study, ovarian HK1, HK2, PDHX and ACSS2 were repressed but FBP2 and ALDH1B1 were activated in DHT-treated rats, further complicating the metabolic disorders in those groups." (PMID 25887459, 2015).
FBP2 also shares sentences with these, for which no sentence is quoted: diabetes (2 papers); non-small cell lung carcinoma (2); brain disorder (1); cardiovascular disease (1); colon cancer (1); COVID-19 (1); endocervical adenocarcinoma (1); gastric tumours (1); glioblastoma (1); glioma (1); Hyperglycemia (1); kidney disease (1); melanoma (1); myocardial infarction (1); myopathy (1); preeclampsia (1); viral infection (1).